PSG9 (pregnancy specific beta-1-glycoprotein 9)
Diseases named in the same sentence as PSG9 in open-access papers (continued):
Sharing a sentence is not in itself a finding about the gene and the disease.
breast tumors (1 paper, 2020). "In this study, we provide the first evidence that PSG9 expression levels are associated with the metastatic phenotype of breast tumors and shorter patient survival." (PMID 33377651, 2020). "The noted upregulation of PSG9 mRNA levels in breast tumors was further confirmed in the Oncomine cancer microarray database (Finak Breast Dataset39)." (PMID 33377651, 2020). "Results showed that PSG9 levels were elevated in primary breast tumor tissues, particularly in metastatic LNs, compared to matched normal breast tissues." (PMID 33377651, 2020). "To validate these results, we examined PSG9 protein levels in nine pairs of matched adjacent normal breast tissues, primary breast tumors, and metastatic lymph node (LN) tissues by immunoblotting with an anti‐PSG9 antibody." (PMID 33377651, 2020). "The mRNA levels of PSG9, but not other PSGs, were significantly upregulated in breast tumors relative to normal breast tissues." (PMID 33377651, 2020). "Moreover, breast tumors with distant metastasis expressed higher levels of PSG9 than those without metastasis." (PMID 33377651, 2020).
colon cancer (1 paper, 2005). "The RKO colon cancer cell line exhibited the lowest level of PSG9." (PMID 15982419, 2005).
colorectal tumours (1 paper, 2005). "Primary sporadic colorectal tumours, liver metastasis and corresponding normal tissues were also examined for PSG9 expression by semi- and quantitative PCR." (PMID 15982419, 2005).
Familial adenomatous polyposis (1 paper, 2016). Familial adenomatous polyposis (FAP) is characterized by the development of hundreds to thousands of adenomas in the rectum and colon during the second decade of life. "The abnormally high levels of PSG9 detected in cases of familial adenomatous polyposis (FAP) and in adenomas may promote colorectal carcinogenesis." (PMID 27528036, 2016).
lymph node metastasis (1 paper, 2021). "Additionally, we also confirmed the cancer-regulating function of miR-16 family/TFAP2A/PSG9 axis in LUAD clinical specimens, especially for lymph node metastasis." (PMID 33824285, 2021).
rectal cancer (1 paper, 2005). A primary or metastatic malignant neoplasm that affects the rectum. "Northern blot analysis showed clear expression of three PSG9 transcripts in colon and rectal cancer, and two transcripts in uterine cancer." (PMID 15982419, 2005).
tumor (5 papers, 2005 to 2022). "Another possibility is that upregulation of PSG9 might favour tumour development by causing a reversion of the monolayered adult colonic epithelium to an embryonic multilayered arrangement." (PMID 15982419, 2005). "Deregulation of PSG9 variants could be detected in most tumours and liver metastases tested." (PMID 15982419, 2005). "Consistent with in vitro results, ectopic expression of PSG9 significantly promoted tumor growth in mice implanted with MDA‐231 cells stably expressing HA‐PSG9 as compared with mice implanted with pCDH expressing control cells." (PMID 33377651, 2020). "Fourth, both in vitro and in vivo functional assays demonstrated that PSG9 promotes tumor growth and metastasis." (PMID 33377651, 2020). "Results showed that knockdown of PSG9 reduced the number of metastatic tumor nodes in the lungs of mice." (PMID 33377651, 2020). "We discovered that PSG9 was significantly increased in serum (P<0.001) and in tumor tissues (P<0.001) from patients with CRC." (PMID 27528036, 2016). "As expected, the upregulation PSG9 either in HT-29 or HCT-116 cells resulted in significantly higher proliferation rates for tumor xenografts in mice." (PMID 27528036, 2016). "We detected more vessels in tumor xenografts from mice injected with stable PSG9-transfected HT-29 or HCT-116 cells." (PMID 27528036, 2016). "It was not only consistence with our finding that PSG9 activated the TGF-β pathway, but also proved that PSG9 limited anti-tumor immunity and polarized microenvironment to a more pro-angiogenic microenvironment." (PMID 27528036, 2016). "In normal-appearing epithelial cells in FAP, PSG9 was expressed mostly on the apical surface, while in tumours, expression was detected from the top to the base of crypts." (PMID 15982419, 2005). "The degree of PSG9 expression in the tumour samples appears to be related to differentiation, with highly differentiated cells expressing the highest levels." (PMID 15982419, 2005). "The expression pattern of PSG9 also varied between different tumours and cell lines although the significance of these differences is unclear." (PMID 15982419, 2005). "It is also possible that PSG9 expressed by pre-malignant and cancer cells protect tumours from recognition by the body's immune defences." (PMID 15982419, 2005). "Moreover, CRC patients with tumors > 5 cm showed higher serum PSG9 levels than those with tumors ≤ 5 cm, and it was found that PSG9 had the potential to promote tumor cell proliferation." (PMID 27528036, 2016). "High PSG9 levels were found to be related to increased tumor growth." (PMID 27528036, 2016). "The overexpression of PSG9 also increased the growth of tumor xenografts in nude mice." (PMID 27528036, 2016). "We speculated that PSG9 enhanced angiogenesis in this case and thus provided a precondition for rapid tumor growth." (PMID 27528036, 2016). "Upregulated PSG9 in tumor cells might be secreted into the stroma through vesicular transport, where it affects endothelial cell growth in a paracrine manner." (PMID 27528036, 2016). "To examine whether PSG9 expression was specific for tumours, we examined expression of PSG2 in the same tumours which had exhibited deregulated PSG9 expression." (PMID 15982419, 2005). "Next, we examined whether the PSG9 expressed in tumours was different from PSG9 expressed by placental cells during pregnancy." (PMID 15982419, 2005). "We also examined the degree of PSG9 expression in a panel of RNAs extracted from different tumours." (PMID 15982419, 2005). "Next, we asked whether PSG9 overexpression promotes the formation of tumor xenografts." (PMID 27528036, 2016). "Together, our findings illustrate the innovative mechanism by which PSG9 drives the progression of CRC and tumor angiogenesis." (PMID 27528036, 2016). "Conversely, knockdown of PSG9 in LM2‐4175 cells slowed down tumor growth than scramble controls, even no tumors were observed in some mice." (PMID 33377651, 2020).
tumor (continued). "We also explored whether PSG9 is a key component in the regulation of TGF-β signaling-induced tumor angiogenesis via enhancement of nuclear retention of SMAD4, and finally, we determined whether the expression of proangiogenic molecules is affected by the PSG9/SMAD4 interaction." (PMID 27528036, 2016).
cancer (4 papers, 2005 to 2021). A tumor composed of atypical neoplastic, often pleomorphic cells that invade other tissues. "In clinical specimens, we also validated cancer-regulating effect of miR-16 family/TFAP2A/PSG9 axis, especially for lymph node metastasis of LUAD." (PMID 33824285, 2021). "Our findings that the overexpression of PSG9 promotes cancer cell growth and vasculogenesis provide insights into mechanisms and strategies for therapeutic intervention in advanced CRC." (PMID 27528036, 2016). "Reports that PDGF-AA promotes cancer cell proliferation are consistent with our findings of PSG9 function on cell proliferation." (PMID 27528036, 2016). "In cancer tissues, 31 (41.89%) cases displayed high PSG9 expression." (PMID 27528036, 2016). "In summary, our findings indicate that the interaction of PSG9 with the transcription factor SMAD4 promotes its functions and is therefore critical for TGF-β-activated expression of angiogenesis-associated genes, cell growth, and cancer metastasis." (PMID 27528036, 2016). "Therefore, our study may provide evidence for novel treatment strategies by targeting PSG9 in antiangiogenic cancer therapy." (PMID 27528036, 2016). "Therefore, we concluded that PSG9 might be secreted by cancer cells into the mesenchyme, where it enhances angiogenesis." (PMID 27528036, 2016). "However, early-onset over-expression of PSG9 in different types of cancer suggests that this gene may be considered as a valuable biochemical tumorigenesis marker." (PMID 15982419, 2005). "Since PSG9 is not found in the non-pregnant adult except in association with cancer, it may be useful as a biomarker for the early detection of cancers of various types." (PMID 15982419, 2005).
PSG9 also shares sentences with these, for which no sentence is quoted: infection (2 papers); autoimmune disease (1); cervical cancer (1); familial colorectal cancer (1); gestational diabetes (1); high blood pressure (1); invasive breast carcinoma (1); Miscarriage (1); pregnancy disorder (1); uterine cancer (1).